TNF (tumor necrosis factor)
Diseases named in the same sentence as TNF in open-access papers (continued):
Sharing a sentence is not in itself a finding about the gene and the disease.
cutaneous vasculitis (6 papers, 2016 to 2025). Inflammation of the blood vessel wall characterized by palpable purpura. "Cutaneous vasculitis in RA patients treated with TNF inhibitors presents a significant diagnostic and therapeutic challenge, requiring careful differential diagnosis and individualized management." (PMID 40385904, 2025). "TNF-α inhibitor-related cutaneous vasculitis was reported in 59.5% of cases (n = 73), while tocilizumab was responsible for only one case (0.8%)." (PMID 41333011, 2025).
discoid lupus erythematosus (6 papers, 2005 to 2026). A chronic, autoimmune skin condition that manifests with a red, scaling rash, most often found on the face, ears, and scalp; these lesions often lead to permanent scarring and dyspigmentation. "By contrast, CLE—particularly discoid lupus erythematosus (DLE)—is often “skin-locked,” with dense interface dermatitis, scarring follicular destruction, and a persistently IFN-high, TNF-low milieu in lesional skin." (PMID 41596733, 2026).
disseminated tuberculosis (6 papers, 2010 to 2023). "We do note a case of development of miliary tuberculosis after an IA TNF-i injection." (PMID 34525992, 2021). "In addition, as we have discussed, anti-TNF-α therapy induces disseminated tuberculosis, obstructing granuloma formation." (PMID 25317081, 2014).
encephalomyelitis (6 papers, 2015 to 2025). Inflammation of the brain and the spinal cord. "Activation of NF-κB can regulate the release of TNF-α and IL-1β in the hippocampus, which is responsible for inflammatory diseases of the central nervous system." (PMID 36999158, 2023).
endocarditis (6 papers, 2015 to 2024). Inflammation of the endocardium. "Reports have even highlighted instances where immunomodulatory therapies, including monoclonal antibodies and TNF-α blockers, inadvertently exacerbated WD, leading to severe complications such as endocarditis." (PMID 39310504, 2024). "Further evidence suggests there may be a correlation between the use of immunomodulators, particularly tumor necrosis factor-alpha (TNF-α) inhibitors, and the incidence of endocarditis in WD patients." (PMID 39310504, 2024). "TNFα blockade may indeed have changed the clinical course of the disease from an indolent infection with RA phenotype to a more typical presentation of Aa endocarditis (e.g., septic emboli)." (PMID 30459755, 2018). "Monocytes of patients with endocarditis, which were not able to eliminate C. burnetii, secreted high levels of TNF in response to C. burnetii." (PMID 26783541, 2015).
experimental arthritis (6 papers, 2012 to 2019). ARTHRITIS that is induced in experimental animals. "IL-1β and TNF-α are the main inflammatory cytokines in the body, which play an important role in the pathogenesis of RA or experimental arthritis synovitis." (PMID 29743895, 2018). "Cytokines such as interleukin-1-beta (IL-1β), tumor necrosis factor-alpha (TNF-α), and interleukin-6 (IL-6) have been shown to display potent proinflammatory actions and to contribute to the pathogenesis of RA or experimental arthritis, particularly to cartilage and bone damages." (PMID 22414623, 2012).
follicular lymphoma (6 papers, 2009 to 2025). Follicular lymphoma is a form of non-Hodgkin lymphoma characterized by a proliferation of B cells whose nodular structure of follicular architecture is preserved. "In addition, we found evidence of associations between elevated levels of TNF-α and DLBCL and follicular lymphoma subtypes." (PMID 30873511, 2018).
frontotemporal dementia (6 papers, 2008 to 2021). Frontotemporal dementia (FTD) comprises a group of neurodegenerative disorders, characterized by progressive changes in behavior, executive dysfunction and language impairment, as a result of degeneration of the medial prefrontal and frontoinsular cortices. "Frontotemporal dementia (FTD) patients showed increased CSF TNF-α and TGF-β." (PMID 23841061, 2013).
fungal keratitis (6 papers, 2018 to 2024). "Transcriptome analysis of fungal keratitis revealed inflammatory cytokine genes, i.e., IL-1B, IL-6, TNF- α, to be significantly associated with fungal keratitis." (PMID 35328532, 2022). "Former research in fungal keratitis indicated that inflammatory cytokines, IL-1β, IL-6, TNF- α, as well as Wnt, Hippo, and cGMP-PKG signaling pathways were significantly associated with the disease." (PMID 36838330, 2023). "In the current study, we investigated the expression of histone H3 (H3), acetylated histone H3 (AC-H3), HDAC1, TLR4, TNFα, and IL-1β in corneal specimens from patients with fungal keratitis and mice with experimental fungal keratitis." (PMID 31285488, 2019). "This was corroborated by results of real-time PCR at mRNA levels of TLR4, TNFα and IL-1β, as well as the ELISA results at protein levels of TNFα and IL-1β of the corneal specimens from mice with fungal keratitis." (PMID 31285488, 2019). "IL-10 and TNF-α levels in the aqueous humor of fungal keratitis patients were higher on average than those of the control, but with no statistical differences." (PMID 29673332, 2018). "In this study, MMP9, along with other MMPs (MMP1, MMP7, MMP10, MMP12), pro-inflammatory cytokines (IL1B, TNF), and PRRs (TLR2, TLR4), were upregulated in bacterial and fungal keratitis." (PMID 35328532, 2022). "In the current study, we found that there was abundant expression of TNFα and TLR4 in the specimens from patients with fungal keratitis and mice with experimental fungal keratitis." (PMID 31285488, 2019). "SAHA was able to inhibit experimental fungal keratitis by suppressing TLR4 and inflammatory cytokines (TNFα, IL-1β) and inhibition of HDAC may be a potential therapeutic approach for the treatment of fungal keratitis." (PMID 31285488, 2019). "It was found that the expression of mRNA of TLR4, TNFα and IL-1β of the corneal specimens from mice with fungal keratitis was significantly suppressed after SAHA treatment compared with control, the production of TNFα and IL-1β was also inhibited with SAHA treatment as shown by ELISA assay." (PMID 31285488, 2019). "SAHA was able to inhibit experimental fungal keratitis in mouse by suppressing TLR4 and inflammatory cytokines such as TNFα and IL-1β; the inhibition of HDAC may be a potential therapeutic approach for the treatment of fungal keratitis." (PMID 31285488, 2019).
glucocorticoid resistance (6 papers, 2015 to 2025). "For example, mitogen-activated protein kinase (MAPK), protein kinase C (PKC) and phosphoinositide 3-kinase (PI3K) pathways are all activated by TNF and have been implicated in the induction of glucocorticoid resistance." (PMID 25625944, 2015). "Next, the potential of this Belinostat treatment was tested in a TNF-induced glucocorticoid resistance model." (PMID 28686666, 2017). "The fluctuation of TGFβ1 and TGFBR2 allowed us us to speculate that such configuration may favor TNFα pro-inflammatory signaling to induce an acute form of glucocorticoid resistance (GCR)." (PMID 37301958, 2023). "In adipose tissue, the development of glucocorticoid resistance by tumour necrosis factor α (TNFα) treatment was also shown to inhibit GR function by promoting the expression of GRβ, a nuclear localized GR isoform which acts as a dominant negative of GRα transcriptional activity." (PMID 32958048, 2020).
Guillain-Barre syndrome (6 papers, 2012 to 2024). A spectrum of rare post-infectious neuropathies that usually occur in otherwise healthy patients. "Lipooligosaccharides from ganglioside-mimicking bacteria are sufficient to reduce the TNF response against Guillain Barré syndrome-causing bacteria." (PMID 35100875, 2022). "First, TNF-α plays an important role in immune-mediated neuropathies such as Guillain-Barré syndrome, in which small nerve fibers are also involved." (PMID 23304492, 2012).
hemochromatosis (6 papers, 2012 to 2022). A disorder of iron metabolism characterized by a triad of HEMOSIDEROSIS; LIVER CIRRHOSIS; and DIABETES MELLITUS. "TNF-α released in vitro by blood monocytes from patients with hemochromatosis was significantly less than that of control subjects in two studies, but not in a third similar study." (PMID 35659379, 2022). "Quantities of iron removed by phlebotomy and hepatic iron indices in referred hemochromatosis patients with p.C282Y homozygosity were significantly higher in those with TNF -308G → A than in those homozygous for TNF -308G, after adjustment for other factors." (PMID 35659379, 2022). "Taken together, these observations neither confirm nor deny that either TNF-α or TNF alleles influence(s) iron metabolism significantly in patients with hemochromatosis." (PMID 35659379, 2022).
hemorrhagic cystitis (6 papers, 2018 to 2023). Inflammation of the bladder resulting in bloody urine. "The hemorrhagic cystitis induced by IFOS administration also caused a marked increase of TNF-α and IL-1β cytokines when compared with the Sham group." (PMID 35625456, 2022). "The present study provided evidence that IPG exerts anti-inflammatory and antioxidant activities which modulate the hallmarks underlying hemorrhagic cystitis, as it reduced the levels of TNF-α, IL-1β, MDA, and C-reactive protein, as well as increasing SOD levels and reducing edema and hemorrhage." (PMID 35625456, 2022). "Increasing inflammatory mediators such as TNF-α, IL-6, and IL-1β in hemorrhagic cystitis will further aggravate the inflammatory response." (PMID 34804174, 2021). "Further, TNF-α was shown to play a role in CP-induced apoptosis in vascular endothelial cells and hemorrhagic cystitis." (PMID 32033362, 2020). "Other candidate drugs for ifosfamide-induced hemorrhagic cystitis have also been shown to specifically target the IL-1β-TNFα-IL-6 pathway." (PMID 30733505, 2019). "Another potential approach to treat chemotherapy-induced hemorrhagic cystitis is to administer IL-412, a potent anti-inflammatory cytokine known to antagonize the IL-1β, TNFα and IL-6 pathways." (PMID 30733505, 2019). "The suppression of ERK phosphorylation by DADS is related to the protective effects against cyclophosphamide-induced hemorrhagic cystitis in rats and the inhibitory effects of TNF-α-induced production of monocyte chemotactic protein-1 in MDA-MB-231 cells." (PMID 30400352, 2018). "Candidate drugs targeting the inflammatory IL-1β, TNFα and IL-6 triad and/or promoting antioxidant responses show promise for ameliorating hemorrhagic cystitis but have not progressed beyond preclinical testing." (PMID 30733505, 2019). "Besides effects on the IL-1β, TNFα and IL-6 triad, IPSE may also mediate critical gene expression changes in chemokines during ifosfamide-induced hemorrhagic cystitis." (PMID 30733505, 2019).
Hyperkalemia (6 papers, 2013 to 2025). An abnormally increased potassium concentration in the blood. "Splenectomy prevented most of TAK981-induced immune and metabolic effects, including TNFα production, hyperkalemia, HAGMA, and kidney dysfunction markers blood urea nitrogen and creatinine." (PMID 37520526, 2023). "This higher TNFα production induced by SUMO1-null splenocytes also triggered the responses observed in SUMO1-null mice, including higher hyperkalemia and anion gap levels." (PMID 37520526, 2023). "Following TNFα responses, SUMO1-null mice also had higher hyperkalemia, HAGMA, blood urea nitrogen, and creatinine levels." (PMID 37520526, 2023). "Of note, hyperkalemia and creatinine levels mimicked TNFα responses, but not in SUMO3-null mice as they had similar TNFα responses than wild-type mice, but higher HAGMA and blood urea nitrogen." (PMID 37520526, 2023).
Hypomagnesemia (6 papers, 2022 to 2024). An abnormally decreased magnesium concentration in the blood. "Hypomagnesemia promotes chronic low-grade inflammation, and the levels of inflammatory cytokines (TNF-α and IL-6) are increased in Mg-deficient rodents." (PMID 34541392, 2022). "This group exhibited inflammatory activity (LBP and TNFα) contributing to clinically significant hypomagnesemia." (PMID 36232646, 2022). "Also, hypomagnesemia enhances inflammation by promoting inflammatory genes such as TNF-α and IL-6, which suppress osteoblast function and promote osteoclast function." (PMID 38247490, 2024). "In addition, magnesium is also an anti-inflammatory factor, and hypomagnesemia increases the inflammatory environment in obese patients, significantly increasing the levels of IL-1 and TNF-α." (PMID 37327293, 2023).
IgA vasculitis (6 papers, 2021 to 2025). "Although the coexistence of HS and IgA vasculitis is exceedingly rare, previous reports have implicated biologic agents such as tumor necrosis factor (TNF)-α inhibitors, including adalimumab." (PMID 41567199, 2025). "We present two case reports of patients who developed drug-induced IgA vasculitis (IgAV) during TNF inhibitor therapy and discuss the treatment options." (PMID 38124070, 2023). "On the contrary, several recent reports suggest a possible pathogenetic role of TNF-mediated immune reactions in IgA vasculitis." (PMID 34299162, 2021). "Another study showed that six out of nine patients experienced IgA vasculitis onset during TNF inhibitors; however, three of five patients continued to use TNF inhibitors and fully recovered while maintaining TNF inhibitor treatment." (PMID 34299162, 2021). "Some complex cytokine pathways, such as IFN, might also be involved in TNF inhibitor-related IgA vasculitis." (PMID 34299162, 2021). "As shown in TNF inhibitor-mediated IgA vasculitis, it seems that the involvement of TNF is not simple in the pathogenesis of IgA vasculitis." (PMID 34299162, 2021).
inflammatory breast carcinoma (6 papers, 2017 to 2025). An advanced, invasive breast adenocarcinoma characterized by the presence of distinct changes in the overlying skin. "It was found that the expression of the cell TNF-α in inflammatory breast carcinoma is related to the grade of the tumour." (PMID 35928364, 2022). "In inflammatory breast cancer (IBC), activated T cells could release soluble factors (TNF-α, IL-6, and TGF-β) to facilitate the expression of EMT-related genes, including FN1, VIM, TGM2 and ZEB1, thereby promoting EMT." (PMID 35251963, 2022).
juvenile dermatomyositis (6 papers, 2013 to 2024). Juvenile dermatomyositis (JDM) is the early-onset form of dermatomyositis (DM), a systemic, autoimmune inflammatory muscle disorder, characterized by proximal muscle weakness, evocative skin lesion, and systemic manifestations. "For example, TNFα -308A allele was associated with higher serum interferon-alpha levels in the patients with juvenile dermatomyositis." (PMID 23717605, 2013). "There are approximately 56 other patients and 63 courses of therapy reported in the literature regarding the use of anti-TNF-α agents in patients affected by DM/PM or juvenile DM." (PMID 24600322, 2014). "In addition, HSP60 (10 μg/ml) has been reported to induce significant amounts of TNF-α, IL-1 and IL-10 from peripheral blood mononuclear cells of patients with juvenile dermatomyositis." (PMID 25915936, 2015). "Even juvenile dermatomyositis (JDM) has been associated with TNF-α and IL-1 cytokines genetic polymorphisms, and TNF-α levels have been shown to correlate with disease activity." (PMID 34198614, 2021). "Anti-TNF treatment may be useful for the treatment of patients with refractory juvenile dermatomyositis (JDM)." (PMID 32293539, 2020).
Legionnaires' disease (6 papers, 2016 to 2024). A pneumonia caused by Legionella pneumophila and other Legionella species, which is characterized by fever, cough, progressive respiratory distress, and which is often accompanied by extrapulmonary manifestations. "Indeed, anti-TNF therapy is a recognized risk factor for Legionnaire's disease, suggesting a role for TNF in the immune response to L. pneumophila." (PMID 27105352, 2016). "Indeed, patients with Legionnaires’ disease show increased level of IL-6 and TNFα in their lungs." (PMID 26741365, 2016).
Lipedema (6 papers, 2020 to 2025). Disorder of adipose tissue characterized by symmetric and bilateral enlargement of the lower extremities due to abnormal deposition of subcutaneous fat often in obese women. "TNF-α is associated with oxidative stress, a condition present in lipedema." (PMID 40125475, 2025). "Recent studies have reported elevated serum concentrations of inflammatory markers such as CRP (C-reactive protein) and TNF-α (tumor necrosis factor-alpha) in lipedema patients." (PMID 41010539, 2025). "A trend of elevated expression of VEGF, IL-6, IL-1ß, and TNFα in differentiated lipedema adipocytes compared to controls was observed by Al-Ghadban, principally in adipose tissue derived from the thigh but not abdomen of donors." (PMID 36675759, 2022). "Concomitant with higher oxidative stress parameters, we found higher TNFα concentrations in lipedema compared to the control group (p<0.05)." (PMID 36387874, 2022). "Given the higher levels of TNFα and oxidative stress markers in lipedema patients compared to the control group, we further sought to investigate the pattern of pro-inflammatory markers in both groups." (PMID 36387874, 2022). "In both groups, TNFα levels positively correlated with insulin concentrations (lipedema: r=0.605; p=0.029; control: r=0.733; p=0.004)." (PMID 36387874, 2022). "Similarly, the plasma concentration of TNFα (established marker of systemic inflammation) positively correlated with age only in lipedema patients." (PMID 36387874, 2022). "Interestingly in the lipedema group, insulin (r=0.577; p=0.039), TNFα (r=0.741; p=0.004), total cholesterol (r=0.662; p=0.014) and LDL-C concentrations (r=0.693; p= 0.009) were positively associated with age while none of these correlations was significant for the control group." (PMID 36387874, 2022). "Finally, TNFα concentration was positively associated with HbA1c in the control group (r=0.693; p=0.009) and not in the lipedema group (r=-0.149; p=0.626)." (PMID 36387874, 2022). "Recent studies found that ketogenic diet may lower levels of systemic inflammatory markers (TNF-α and CRP) in patients with lipedema." (PMID 41010539, 2025). "A significant decrease of IL-8 but not IL-6, IL-1ß or TNFα was found in supernatants from lipedema SVFs." (PMID 36675759, 2022). "Moreover, TNF-α concentrations have been found to be increased in patients with lipedema compared with BMI-matched controls without lipedema." (PMID 40125475, 2025).
Liver abscess (6 papers, 2011 to 2025). A circumscribed area of pus or necrotic debris in the liver. "It promoted liver repair, inhibited amoebae presence, and modulated inflammatory cytokines (TNF-α, IL-1β, IL-10), reducing liver abscess progression to just 9.49%, compared to 84% in untreated animals." (PMID 40077770, 2025). "The results for expression levels of TNF-α, IL-6 and IL-1β in tissue at the edge of liver abscesses were similar to the immunohistochemistry data." (PMID 29420539, 2018). "When stimulated with amoebic proteins, macrophages isolated from hepatic abscesses in the initial stages of infection produced large concentrations of TNF-a." (PMID 21356065, 2011). "A study using mice model demonstrated that K. pneumoniae strains from pyogenic liver abscess exhibited higher virulence in diabetic than in nondiabetic mice and significantly decreased the blood cytokine TNF-alpha level." (PMID 37193729, 2023).
liver toxicity (6 papers, 2014 to 2025). "Our results indicate, by measuring TNF-α andIL-1β levels, an inflammation reaction in the liver, suggesting that NP exposure duringpregnancy and breastfeeding led to liver toxicity through increased liverpro-inflammatory cytokines." (PMID 27982282, 2016). "Although, despite production of pro-inflammatory cytokines such as IL-1β, IL-6, and TNF, TNF-deficient mice were not protected from APAP liver toxicity and mice lacking TNFR1 even developed aggravated liver damage." (PMID 35122118, 2022).